RNU6-4P (RNA, U6 small nuclear 4, pseudogene)
Synonyms: U6-4; RNU6-4
Gene: Small nuclear RNA gene on chromosome 3 (181,231,737 to 181,231,843, forward strand). Ensembl gene ENSG00000206932.
Homologues: Orthologues: chimpanzee U6 (100% identical), mouse Gm24873 (100% identical), rat U6 (100% identical). Paralogues in human: RNU6-1 (100% identical), RNU6-2 (100% identical), RNU6-3P (100% identical), RNU6-5P (100% identical), RNU6-6P (100% identical), RNU6-9 (100% identical), RNU6-12P (99% identical), RNU6-13P (99% identical), RNU6-17P (99% identical), RNU6-18P (99% identical), RNU6-25P (99% identical), RNU6-32P (99% identical), and 1288 more.